PTPN14 (protein tyrosine phosphatase non-receptor type 14)
Diseases named in the same sentence as PTPN14 in open-access papers (continued):
Sharing a sentence is not in itself a finding about the gene and the disease.
tumor (continued). "Moreover, PTPN14 can function as a tumor suppressor by negatively regulating Yap signaling." (PMID 34815476, 2021). "miR-21 facilitates tumor growth, survival, and invasion by targeting a range of tumor suppressor genes, including PTEN, PDCD4, and PTPN14." (PMID 41008657, 2025). "As a cytoplasmic phosphatase, PTPN14 retains YAP in the cytoplasm in a phosphatase-independent manner, effectively inhibiting tumor cell proliferation and migration." (PMID 41256331, 2025). "Several potential substrates for PTPN14, including β-catenin, p130Cas, RIN1 and PRKCD, and YAP, are all related to tumor progression and metastasis." (PMID 35135548, 2022). "Previous studies have shown that PTPN14 is a tumor suppressor that regulates Yap/Hippo signaling, and Yap can be a major effector of mutant KRAS during tumor progression." (PMID 34815476, 2021). "Due to the critical functions of its target proteins in various signaling pathways, miR-21 plays an important role in tumor progression and apoptosis by regulating specific target mRNAs, and we identified PTEN and PTPN14 as direct targets of miR-21 in ICC." (PMID 25803229, 2015). "We also confirmed that miR-21 promoted cell proliferation and tumor growth via direct repression of PTEN and PTPN14 expression." (PMID 25803229, 2015). "We and others have determined that many HPV E7 proteins also target a second tumor suppressor, Protein Tyrosine Phosphatase Non-receptor Type 14 (PTPN14) (18, –, 20)." (PMID 39248565, 2024). "The phosphatase domain of PTPN14 likely lacks enzymatic function and the putative catalytic site does not appear important for tumor suppressive activity." (PMID 38496413, 2024). "We previously identified Protein Tyrosine Phosphatase Non-Receptor Type 14 (PTPN14), a tumor suppressor targeted by HPV E7 proteins, as a putative cellular target of MmuPV1 E7." (PMID 37036883, 2023). "We next sought to determine whether PTPN14 activity inactivated YAP, and exerted an anti-tumor effect." (PMID 35135548, 2022). "PTPN14 is now considered a tumor suppressor, but its expression and role in AML have not been studied and reported." (PMID 36699453, 2022). "For instance, PTPN14 (Protein Tyrosine Phosphatase Non-Receptor Type 14) is the potential tumor suppressor which owns its involvement in the linkage to the control of Hippo and the Wnt/beta-catenin signaling pathways." (PMID 35989375, 2022). "Furthermore, PTPN14 significantly represses the proliferation, migration, and invasion of HCC cells in vitro and tumor growth and metastasis in vivo." (PMID 35957898, 2022). "We analyzed the expression levels of PTPNs in the TCGA database and discovered that PTPN1, PTPN6, PTPN7, PTPN18, PTPN20, and PTPN22 were significantly upregulated in tumor samples, while PTPN4, PTPN5, PTPN10, PTPN11, PTPN13, PTPN14, and PTPN21 were downregulated in tumor samples." (PMID 36226189, 2022). "To determine the prevalence and clinical significance of miR-21 and its direct targets PTPN14 and PTEN in ICC, we assessed the expression of miR-21, PTPN14 and PTEN by miRNA in situ hybridization and IHC staining in tumor tissue samples from 57 ICC patients who received curative resection." (PMID 25803229, 2015). "PTPN14 demonstrated a high immunoreactivity score of 2.4 in the primary tumour, whereas there was no decrease observed in the tumour invasion front (score 2.4)." (PMID 17940512, 2007). "Notably, PTPN14’s role in YAP repression appears not to require its phosphatase activity, and the PTPN14-YAP interaction appears to be the major source of PTPN14 tumor-suppressive activity." (PMID 27651363, 2016). "The non-receptor phosphatase PTPN14, another PTPRK D2 domain interactor, functions as a tumour suppressor and has been suggested to regulate Rab5 to Rab7 endosomal maturation, impacting on EGFR signalling." (PMID 38904097, 2024).
cancer (36 papers, 2007 to 2025). A tumor composed of atypical neoplastic, often pleomorphic cells that invade other tissues. "PTPN14 is mutated in several cancers, and our subsequent studies will investigate the effect of restoration of PTPN14 levels in HPV-positive cancer cells." (PMID 27651363, 2016). "Other cancers with PTPN14 mutations include pancreatic adenocarcinomas, basal cell carcinomas, and relapsed neuroblastomas as well as 13.2% of cell lines in the NCI-60 set (36, –, 38)." (PMID 27651363, 2016). "The association of PTPN14 with several cancers led to our particular interest in PTPN14 as a target of HPV E7 proteins from diverse virus types." (PMID 27651363, 2016). "We next asked whether the gene expression pattern observed downstream of PTPN14 loss is reflected in HPV-positive cancers." (PMID 35170430, 2022). "The gene encoding PTPN14 has been implicated as a cancer gene." (PMID 27651363, 2016). "One clue could lie in PTPN14, a human protein which many papillomaviruses eliminate using their viral E7 protein; this mechanism could be essential for the virus to replicate and cause cancer." (PMID 35170430, 2022). "Taken together, the experimental metastasis model indicated the inhibitory role of PTPN14 in cancer invasiveness." (PMID 39189475, 2024). "The CNV percentage in pan-cancer indicated that heterozygous amplification in cancers were widely found in genes PTPN1, PTPN7, PTPN12 and PTPN14 in most cancers, while heterozygous deletions were widely found in genes PTPN13, PTPN20, PTPN22 and PTPN23." (PMID 37884566, 2023). "Overall, these findings highlight that disruption of cell polarity by KRASG12V acts through PTPN14 and highlight its pivotal functions in apical-basal polarity organization during cancer progression." (PMID 34815476, 2021). "In the last decade, many studies strongly suggest that several phosphatases (e.g., PP2A, PP1, STRIPAK, PTPN14, etc.)can regulate cancer cell proliferation, cell migration, and genetic instability through interaction with the Hippo pathway." (PMID 32867200, 2020). "A wealth of information about the role of PTPN14 in cancer is available; however, much less has been reported about its effects on the immune response." (PMID 32978373, 2020). "After the previous findings, groups became interested in the possible relationship of PTPN14 to other signaling pathways involved in the maintenance of cancer cells." (PMID 27240404, 2016). "In this review, we summarize the current and emerging regulatory roles of KIBRA and PTPN14 in the Hippo pathway and their functions in cancer." (PMID 27240404, 2016). "Based on our results and data from the analysis of PTPN14 in diverse types of cancer, we suggest that epigenetic mechanisms could modulate gene expression; we also propose that aberrant methylation of this gene could contribute to leukemogenesis." (PMID 41226303, 2025). "These promising results may pave the way for the translational application of PTPN14 in cancer therapy, potentially extending the life expectancy of TNBC patients who have limited treatment options." (PMID 39189475, 2024). "There are many studies of PTPN14 in cancer, indicating that PTPN14 plays a vital role in cancer." (PMID 36898991, 2023). "Therefore, the characterization of new substrates of this phosphatase is important to understand the role of PTPN14 in cancer progression." (PMID 32152405, 2020). "However, in situations where PTPN14 expression is relatively low (endogenous expression in cancer cells), E-cadherin expression becomes necessary to promote CAV1 dephosphorylation and thereby preclude CAV1-mediated migration, invasion, and metastasis." (PMID 32152405, 2020).
cancer (continued). "Although low-risk and non-cancer-associated E7 proteins engage both PTPN14 and UBR4, we hypothesize that the more robust interaction of high-risk E7 with both proteins is responsible for the high-risk E7-specific degradation of PTPN14." (PMID 27651363, 2016). "MiR-21 also plays an oncogenic role in other cancers by targeting the forkhead box O1 (FOXO1), protein tyrosine phosphatase non-receptor type 14 (PTPN14), and PTEN." (PMID 38559560, 2024). "As such, special attention in future analyses should be paid to the linking genes PRKCA, PTPN14, POU2F1, and TGFBR1, because of their possible roles in cancer initiation." (PMID 30045691, 2018). "Other known Hpo-independent regulators of Yki include the phosphatase PTPN14 and the WW domain binding protein WBP2, which were identified in mammalian cancer cell lines." (PMID 25643260, 2015). "In particular, compared to the untreated group, the extract increased the expression of the tumor suppressor genes LATS2 and PTPN14 in HCT116 cells and decreased the expression of the oncogenes YAP1 and TEAD2 in HT29 cells, suggesting targeted modulation of cancer cell growth." (PMID 41516111, 2025). "Additionally, we identified breast cancer antiestrogen resistance 3 (BCAR3) as a novel substrate responsible for the suppression of the PI3K/AKT and ERK pro‐survival pathways by PTPN14." (PMID 39189475, 2024). "Finally, we show that PTPN14 overexpression blocks CAV1-enhanced migration, invasion, and metastasis of cancer cells due to its catalytic activity." (PMID 32152405, 2020). "The identification of inactivating mutations in two key components of the Hippo–YAP pathway, LATS1 and PTPN14 genes, provides clear evidence of the involvement of this signaling cascade in BCC, adding BCC to the broad group of human cancers with a deregulated Hippo–YAP axis." (PMID 29165358, 2017). "YAP1 activation and PTPN14 are relevant to both viral and nonviral cancers." (PMID 35170430, 2022). "PTPN14 is a nonreceptor protein tyrosine phosphatase that is involved in regulating a variety of cellular processes, including cell adhesion, cell growth, differentiation and cancer progression." (PMID 35135548, 2022).
infection (4 papers, 2018 to 2024). The state of being infected such as from the introduction of a foreign agent such as serum, vaccine, antigenic substance or organism. "At 20 h post-infection, PTPN14-deficient mice showed a slighter liver injury, whereas wild-type mice developed a severe inflammation." (PMID 32978373, 2020). "Because a previous report indicated that PTPN21 is another regulator of the Hippo pathway signaling that interferes with YAP activity, as does PTPN14, it might be reasonable to hypothesize that HPV targets PTPN21 via its E7 protein during infection." (PMID 31323018, 2019). "For example, protein tyrosine phosphatase, non-receptor type 14 (PTPN14) protein was downregulated >12-fold during infection, but the transcript was downregulated 1.1- to 1.4-fold as opposed to being upregulated, which was a requirement of the screen." (PMID 30122656, 2018).
PTPN14 also shares sentences with these, for which no sentence is quoted: colon cancer (3 papers); choanal atresia (2); triple-negative breast carcinoma (2); acute lung injury (1); adenocarcinoma (1); Alzheimer disease (1); Ataxia-telangiectasia-like disorder 1 (1); clear cell renal cell carcinoma (1); colorectal tumours (1); ductal carcinomas (1); gall bladder cancer (1); glioma (1); hereditary lymphedema III (1); invasive ductal breast carcinoma (1); leukemia (1); lipoma (1); lung injury (1); lymphangiectasia (1); neurological diseases (1); Noninsulin Dependent Diabetes (1); Pulmonary arteriovenous malformation (1); skin basal cell carcinoma (1); stomach adenocarcinoma (1).